RNU7-93P (RNA, U7 small nuclear 93 pseudogene)
Gene: Small nuclear RNA gene on chromosome 14 (36,405,214 to 36,405,274, forward strand). Ensembl gene ENSG00000238540.
Homologues: Orthologues: macaque U7 (100% identical). Paralogues in human: RNU7-20P (77% identical), RNU7-124P (75% identical), RNU7-143P (75% identical), RNU7-37P (75% identical), RNU7-40P (75% identical), RNU7-102P (74% identical), RNU7-120P (74% identical), RNU7-24P (74% identical), RNU7-7P (74% identical), RNU7-81P (74% identical), RNU7-10P (72% identical), RNU7-123P (72% identical), and 141 more.